CCBE1 (collagen and calcium binding EGF domains 1)
Description:
Required for lymphangioblast budding and angiogenic sprouting from venous endothelium during embryogenesis.
Synonyms: KIAA1983; FLJ30681; HKLLS1
Tractability: Antibody: UniProt places it where antibodies can reach, with high confidence; its Gene Ontology location is reachable by antibodies, with high confidence; UniProt predicts a signal peptide or a membrane-spanning region; the Human Protein Atlas places it where antibodies can reach.
Gene: Protein-coding gene on chromosome 18 (59,430,939 to 59,697,694, reverse strand). Ensembl gene ENSG00000183287.
Subcellular location: Secreted
Subcellular location (Human Protein Atlas): Cytosol; Plasma membrane; Predicted to be secreted
Gene Ontology:
Molecular function: collagen binding; protease binding; protein binding; calcium ion binding
Biological process: lymphangiogenesis; positive regulation of protein processing; positive regulation of vascular endothelial growth factor production; positive regulation of vascular endothelial growth factor signaling pathway; sprouting angiogenesis; venous blood vessel morphogenesis; positive regulation of angiogenesis; positive regulation of lymphangiogenesis
Cellular component: extracellular matrix; extracellular region
Genetic constraint (gnomAD): Loss-of-function variants: 33 observed, 47.32 expected, observed/expected ratio (o/e) 0.7, 90% interval 0.53 to 0.93. The upper end of that interval is the gene's LOEUF score, 0.93, which puts it in group 3 of 6, group 1 being the genes least tolerant of losing a copy. Missense variants: 517 observed, 516.13 expected, observed/expected ratio (o/e) 1, 90% interval 0.93 to 1.08. Synonymous variants: 226 observed, 197.98 expected, observed/expected ratio (o/e) 1.14, 90% interval 1.02 to 1.27.
Homologues: Orthologues: chimpanzee CCBE1 (99% identical), macaque CCBE1 (99% identical), pig CCBE1 (92% identical), dog CCBE1 (91% identical), mouse Ccbe1 (90% identical), rabbit CCBE1 (89% identical), rat Ccbe1 (89% identical), guinea pig CCBE1 (88% identical), tropical clawed frog ccbe1 (72% identical), zebrafish ccbe1 (63% identical).
Diseases named in the same sentence as CCBE1 in open-access papers:
CCBE1 is named in the same sentence as 52 diseases in open-access papers, as found by Europe PMC text mining. Sharing a sentence is not in itself a finding about the gene and the disease. The quoted sentences say what the papers report.
Hennekam syndrome (17 papers, 2013 to 2024). Hennekam syndrome is characterized by the association of lymphoedema, intestinal lymphangiectasia, intellectual deficit and facial dysmorphism. "CCBE1 is a secreted molecule involved in lymphatic vasculature development and mutations in CCBE1 were identified in patients with Hennekam syndrome, a rare autosomal recessive disorder of lymphatic development leading to primary LD." (PMID 38177539, 2024). "Hennekam syndrome is due to mutation of CCBE1 (collagen and calcium binding EGF-domain 1) resulting in systemic marked lymphatic dysplasia." (PMID 37241126, 2023). "Mutations in CCBE1 were identified in human patients with Hennekam syndrome (HS), a rare autosomal recessive disorder of lymphatic development that presents a wide variety of symptoms including primary lymphedema, and heart defects." (PMID 35222551, 2022). "In 2009, Alders used homozygosity mapping to identify mutations in the human CCBE1 gene as a cause of Hennekam Syndrome (HS), which is characterized by generalized lymphatic dysplasia." (PMID 33672235, 2021). "Collagen and calcium binding EGF domains 1 (CCBE1) protein is important for lymphatic vessel formation, and deficiency results in lymphedema, and mutations in CCBE1 causes Hennekam syndrome." (PMID 33917579, 2021). "The patient we present here is likely the mildest to be reported to date with mutations in CCBE1 which suggests Hennekam syndrome has an even broader phenotypic variability than previously thought." (PMID 25925991, 2015). "Approximately 25% of patients who have Hennekam syndrome were found to have autosomal recessive mutations in CCBE1 and a further 20% of patients have mutations in FAT4." (PMID 25925991, 2015). "First, in humans, while mutations in CCBE1 are associated with Hennekam syndrome, a disorder characterized by abnormal lymphatic system development, some of these patients present as well congenital heart defects." (PMID 25545279, 2014). "CCBE1 is mutated in some patients with Hennekam syndrome (a form of hereditary lymphedema), and in two families with multiple members having generalized lymphatic dysplasia (GLD), sometimes also with fetal hydrops." (PMID 24086631, 2013). "Importantly, in human, mutations in CCBE1 were found to cause Hennekam syndrome, a congenital disease leading to LD, lymphangiectasia, and heart defects." (PMID 38177539, 2024). "In human patients, mutations in CCBE1 have been found to cause Hennekam syndrome, an inherited disease characterized by malformation of the lymphatic system that presents a wide variety of symptoms such as primary lymphedema, lymphangiectasia, and heart defects." (PMID 35222551, 2022). "Finally, patients with Hennekam syndrome, resulting from mutations in CCBE1, FAT4 or ADAMTS3, exhibit diffuse lymphatic dysplasia which also affects lymph flow in the gut." (PMID 33147779, 2020). "Mutations of the CCBE1 gene cause a highly complex syndrome, the Hennekam syndrome." (PMID 27764183, 2016). "Mutations in the CCBE1 gene have been found in patients with Hennekam syndrome of varying severity." (PMID 25925991, 2015). "Additionally, collagen and calcium-binding EGF domain-containing protein 1 (CCBE1) mutations contribute to defective post-translational proteolytic activation of the VEGF-C ligand in Hennekam’s syndrome, a heritable disease characterized by congenital lymphedema and lymphangiectasia." (PMID 38201272, 2023). "Almost 25% of patient's diseases are influenced by biallelic mutations in CCBE1 (Hennekam lymphangiectasia-lymphedema syndrome 1 (HKLLS1; MIM: 235510)) and FAT4 (Hennekam lymphangiectasia-lymphedema syndrome 2 (HKLLS2; MIM: 616006)) while CCBE 1 gene mutation." (PMID 34234628, 2021). "CCBE1 (Collagen- and Calcium-Binding EGF domain-containing protein 1) is mutated in a cohort of patients with Hennekam syndrome who present abnormal lymphangiogenesis." (PMID 26446156, 2016).
Hennekam syndrome (continued). "Specimens with clinically diagnosed Hennekam syndrome with or without mutations in CCBE1 were compared in the most recent study." (PMID 34234628, 2021). "CCBE1 proteins from Hennekam syndrome patients should be tested in animal models for this purpose." (PMID 34234628, 2021). "This anomaly has never been seen in CCBE1-related disease nor has it been associated with the clinical entity of Hennekam syndrome to our knowledge." (PMID 25925991, 2015). "CCBE1 mutation analysis should be considered in all patients with unexplained lymphatic dysplasia even without the other features of classic Hennekam syndrome." (PMID 25925991, 2015). "A recent report compared individuals with a clinical diagnosis of Hennekam Syndrome with and without mutations in CCBE1." (PMID 25925991, 2015).
colorectal cancer (12 papers, 2020 to 2026). A primary or metastatic malignant neoplasm that affects the colon or rectum. "Mechanistically, this is due to the formation of complexes between Yap/TAZ and TEAD4 in both colorectal cancer cells and cancer-associated fibroblasts, which directly enhance CCBE1 transcription through interaction with its enhancer regions." (PMID 40806273, 2025). "The second group features R-spondin 3 (Rspo3), collagen and calcium binding EGF domains 1 (Ccbe1), and Shisa homolog 3 (Shisa3) genes, potentially relevant to colorectal cancer and therapy." (PMID 41262530, 2026). "Most recently, TGF-ß signaling was reported to negatively regulate CCBE1 during colorectal cancer (CRC) tumor lymphangiogenesis." (PMID 35222551, 2022). "In humans, besides its association with HS, CCBE1 has also been described as relevant protein in several types of cancer such as ovarian, breast and colorectal cancer, as well as gastrointestinal stromal tumor (GIST) and tumor lymphangiogenesis." (PMID 35222551, 2022). "In contrast, CCBE1 is overexpressed in colorectal cancer tissue compared to adjacent tissues, Results showed that CCBE1 overexpression significantly correlates with increased lymph node metastasis, vascular invasion, and liver metastasis." (PMID 34440261, 2021). "Collagen and calcium-binding EGF domain-containing protein 1 (CCBE1) is important for lymphatic vascular development and plays a pro-tumor role in colorectal cancer by promoting lymphangiogenesis and lymphatic metastasis of cancer cells." (PMID 35126454, 2021). "Moreover, it has been found to CCBE1 promotes angiogenesis in colorectal cancer." (PMID 37251946, 2023). "High expression of CCBE1, a novel potential biomarker to predict CRC patients’ prognosis, contributes to the aggressiveness and poor prognosis in Colorectal Cancer patients." (PMID 37985782, 2023). "This upregulation of CCBE1 leads to increased proteolytic activation of VEGF-C, thereby promoting tube formation and migration of human lymphatic endothelial cells in vitro and lymphangiogenesis in a colorectal cancer cell-derived xenograft model in vivo." (PMID 40806273, 2025).
breast carcinoma (11 papers, 2010 to 2023). "To confirm earlier reported results in primary breast carcinomas, we also examined expression of CCBE1 in breast cancer cell lines, in which 8/12 (67%) showed loss of expression as compared with normal breast cell lines." (PMID 19935792, 2010). "Thus, CCBE1 expression is inversely associated with migration of breast cancer cells in vitro." (PMID 19935792, 2010). "CCBE1 is identified as a target gene of miR-330-3p, which is related to the aggressive phenotype of breast cancer." (PMID 35674190, 2022). "Reduced CCBE1 expression has shown to result in increase of invasive capacity in breast cancer cells and to lead to poor clinical prognosis in patients." (PMID 31848385, 2019). "MiR-330-3p was enriched in breast cancer and it targeted CCBE1 to promote the invasion and metastasis of breast cancer cell lines." (PMID 29311822, 2017). "As earlier reported in primary breast cancers, we found that CCBE1 expression was down-regulated in the majority of ovarian cancer cell lines tested and in primary ovarian carcinomas as compared with NOSE." (PMID 19935792, 2010). "Collagen and calcium-binding EGF domains 1 (CCBE1) is an uncharacterised gene that has down-regulated expression in breast cancer." (PMID 19935792, 2010). "Given that CCBE1 expression is also reduced in breast cancer, we alternatively infected T-47D breast cancer cells expressing the murine ecotropic receptor (T-47DmEcoR) with a retroviral vector-expressing full-length CCBE1." (PMID 19935792, 2010). "Together, these studies indicate that CCBE1 is normally expressed in the ovary, but is frequently down-regulated in ovarian and breast cancer." (PMID 19935792, 2010). "The inhibition of MiR-330-3p on target CCBE1 promoted metastasis in human breast cancer." (PMID 37993951, 2023). "As in NSCLC, CCBE1 is also diminished in ovarian cancer and breast cancer." (PMID 32707902, 2020). "CCBE1 overexpression decreases colony formation and migration in T-47D human breast cancer cells." (PMID 32707902, 2020). "Collagen and calcium-binding EGF domains 1 (CCBE1) is an earlier uncharacterised gene of unknown function that has recently been reported to be down-regulated in primary breast carcinomas as compared with matched normal breast tissue." (PMID 19935792, 2010). "Researches found miR-330-3p is correlated with bad prognosis in breast cancer as well, in which miR-330-3p can target Collagen and Calcium Binding EGF Domains 1 (CCBE1) to promote cancer metastasis." (PMID 32948197, 2020). "Among the identified transcripts, downregulation of COL6A2, SERPINA1, CCBE1, TFPI2, THBS1 and COL8A1 have been shown to promote migration and invasion of malign breast cancer cells, aggravate metastatic spread and result in poor prognosis of breast cancer patients." (PMID 31848385, 2019).
lymphedema (8 papers, 2013 to 2025). Excess fluid collection in tissues, causing swelling. "Mutation of the CCBE1 gene causes lymphedema, abnormal development of lymphatic vessels, and other related lymphoid diseases." (PMID 34931668, 2022). "A single amino acid substitution in ADAMTS3, identified from a lymphedema patient, was associated with abnormal CCBE1 localization." (PMID 28687807, 2017). "Other receptors with a collagen-like stretch, COLQ and CCBE1, explain muscle weakness and lymphedema." (PMID 33917579, 2021). "Since the ADAMTS3 R565Q allele was heterozygous in the patient and since it did not completely abolish the interaction of ADAMTS3 with CCBE1, it may not alone explain the lymphedema phenotype, suggesting that it acts as a modifier of the lymphedema phenotype in this family." (PMID 28687807, 2017).
ovarian carcinoma (6 papers, 2010 to 2023). A malignant neoplasm originating from the surface ovarian epithelium. "The only study on the role of CCBE1 in cancer shows that CCBE1 acts as a tumor suppressor gene in ovarian cancer due to methylation causing gene expression silencing." (PMID 34931668, 2022). "We report here that loss of CCBE1 expression is a common event in ovarian cancer, is associated with poor patient outcome and that its loss enhances cancer cell migration and survival, which together suggest that CCBE1 is a new candidate TSG." (PMID 19935792, 2010). "In summary, loss of CCBE1 expression, at least in part due to epigenetic silencing, is common in ovarian carcinomas and confers a migratory and survival advantage to cancer cells." (PMID 19935792, 2010). "Loss of CCBE1 expression in ovarian cancer cell lines was further confirmed by western blotting using a polyclonal antibody raised against CCBE1." (PMID 19935792, 2010). "As CCBE1 maps to 18q21.32, a region frequently exhibiting loss of heterozygosity in ovarian cancer, the aim of this study was to determine the expression and function of CCBE1 in ovarian cancer." (PMID 19935792, 2010). "Loss of CCBE1 expression may, therefore, modulate the migration of cancer cells from the ovary into the peritoneum, a particular characteristic of ovarian carcinomas." (PMID 19935792, 2010). "Loss of CCBE1 expression was significantly associated with higher grade ovarian carcinomas and likely occurs early in ovarian carcinogenesis, with stage I carcinomas expressing lower levels of CCBE1 than NOSE, one predicted cellular origin of ovarian carcinomas." (PMID 19935792, 2010). "The aims of this study were to determine whether CCBE1 expression is lost in ovarian cancer including primary carcinomas, and, given a putative functional link to migration, to determine whether CCBE1 loss affects cancer cell migration and survival." (PMID 19935792, 2010). "However, the downregulation of CCBE1 expression could be detected in ovarian cancer and associated with metastasis, implying a potential organ specific role of CCBE1." (PMID 36906534, 2023). "Thus, loss of CCBE1 expression enhances migration of ovarian cancer cells in vitro." (PMID 19935792, 2010). "This study identifies that CCBE1 expression in ovarian cancer is at least in part regulated by epigenetic mechanisms, in particular promoter hypermethylation." (PMID 19935792, 2010). "Pharmacological demethylation/deacetylation in ovarian cancer cell lines re-induced CCBE1 expression, indicating that epigenetic mechanisms contribute to its silencing in cancer." (PMID 19935792, 2010). "Expression and methylation patterns of CCBE1 were determined in ovarian cancer cell lines and primary tumours." (PMID 19935792, 2010). "CCBE1 mRNA expression was down-regulated or undetectable in 8/11 (73%) ovarian cancer cell lines as compared with normal (immortalised) ovarian surface epithelial cells, as determined using quantitative TaqMan PCR (qPCR)." (PMID 19935792, 2010). "Furthermore, given that a dense region of CG dinucleotides (CpG island) spans its promoter region, a common feature of TSG, we also determined whether loss of CCBE1 expression in ovarian cancer is related to aberrant epigenetic mechanisms, particularly hypermethylation of its promoter." (PMID 19935792, 2010). "siRNA-mediated knockdown of CCBE1 in ovarian cancer cell lines enhanced their migration; conversely, re-expression of CCBE1 reduced migration and survival." (PMID 19935792, 2010). "We used transient transfection of CCBE1-specific siRNAs to knock down expression of CCBE1 in the ovarian cancer cell line CoLo316, which had the highest endogenous protein expression of CCBE1." (PMID 19935792, 2010). "CCBE1 is expressed in normal ovary, but is reduced in ovarian cancer cell lines and primary carcinomas." (PMID 19935792, 2010).